BCR (BCR activator of RhoGEF and GTPase)
Diseases named in the same sentence as BCR in open-access papers (continued):
Sharing a sentence is not in itself a finding about the gene and the disease.
leukemia (continued). "Moreover, imatinib, targeting the TKI BCR–ABL, induces apoptosis via BIM and, to a lesser extent, BAD in BCR–ABL-positive leukemia cells." (PMID 36553449, 2022). "To delineate if initial events of transformation contribute to accelerated leukemia progression in p27-Y88F mice, we expressed v-ABL and BCR::ABL1p190 in bone marrow cells derived from WT and p27-Y88F mice and tested their capacity to form colonies in growth factor-free semisolid media." (PMID 35597806, 2022). "Thus, recently the chemotherapeutic drugs such as imatinib and several tyrosine inhibitors focusing on BCR–ABL gene regulation and related pathways are of great attraction for leukemia treatment researchers." (PMID 35721186, 2022). "The BCR::ABL1 fusion oncoprotein, which has tyrosine kinase activity and activates different downstream signal pathways, such as JAK-STAT, MAPK/ERK, and PI3K/Akt/mTOR, promotes the occurrence and development of leukemia." (PMID 36263131, 2022). "However, tyrosine kinase inhibitors (TKIs) compete with ATP for binding to the active site, inhibiting the BCR::ABL1 activation and preventing leukaemia." (PMID 35884363, 2022). "Around the same time it was recognised that BCR:ABL chimeric proteins were hyperactive tyrosine kinases, that their intrinsic kinase activity was required for cell transformation, and that introduction of BCR:ABL alone produced leukaemias in mice." (PMID 36202796, 2022). "In addition overactivation of three signaling oxidative stress pathways, PI3K/AKT/mTOR, MEK/ERK, and JAK/STAT, and oncogenes such as BCR/ABL and RAS are related to the changes in redox homeostasis in leukemia cells and increases in ROS levels." (PMID 34067520, 2021). "It is well known that BCR/ABL is the oncoprotein and contributes to the development of leukemia." (PMID 34068907, 2021). "About 10% of childhood leukemias have a gene expression profile similar to BCR-ABL-positive leukemia although lacking the actual BCR-ABL fusion protein." (PMID 31970588, 2020). "Previously, NOTCH2, FANCA, BCR, and ROS1 have been described to play an important role in leukemia." (PMID 32638549, 2020). "Nine of the 14 patients (64.3%) had leukemia relapse, and the other five (35.7%) did not achieve a deep molecular response (BCR-ABL transcript level ≤ 0.01%)." (PMID 33014798, 2020). "In the nucleus of bone marrow cells of leukemia patients, In the nucleus of bone marrow cells of leukemia patients, the researchers found that PKM2 can phosphorylate and activate certain transcription factors, thereby inducing fusion of BCR-ABL genes." (PMID 31391918, 2019). "The BCR-ABL gene is formed by mutual translocation between c-ABL on chromosome 9 and BCR on chromosome 22, which activates tyrosine kinase continuously, leading to leukemia-cell proliferation." (PMID 30845905, 2019). "The BCR/ABL fusion gene and its downstream signaling pathways such as Ras/Raf/MAPK, JAK/STAT3, and PI3K/AKT pathways play important roles in malignant transformation of leukemia, especially chronic myelogenous leukemia (CML)." (PMID 29312576, 2017). "Despite the known role of BCR in leukemia, there have been no reports showing any specific function of ABR in myeloid differentiation and AML." (PMID 29262589, 2017). "Both Myb and BCR/ABL proviruses were detected in single methylcellulose colonies formed by the leukemia cells by PCR (data not shown), further suggesting that the transformation requires their expression within the same cell." (PMID 29228732, 2017). "More importantly, both are able to cooperate with BCR/ABL to consistently induce transformation of mouse GMPs and development of aggressive leukemias resembling CML myeloid blast crisis, suggesting that either gene can drive CML progression by promoting the self-renewal of GMPs." (PMID 29228732, 2017).
leukemia (continued). "Interestingly, we found that all mice receiving GMPs co-transduced by BCR/ABL and Hoxa10 viruses also developed myeloid leukemias, although with longer latencies than leukemias induced by Hoxa9+BCR/ABL." (PMID 29228732, 2017). "The 75KDa form also is predominantly expressed in Hoxa9- and Hoxa10-immortalized myeloid progenitors and Hoxa9/Hoxa10+BCR/ABL leukemia cells (data not shown)." (PMID 29228732, 2017). "The distribution of the leukemia cell subpopulations in the samples from patients who expressed BCR/ABL showed little difference to the samples from patients who did not express BCR/ABL." (PMID 27559941, 2016). "Here by searching for novel genotoxic drugs, we identified Bisindolylmaleimide IX, which was shown to be a DNA topoisomerase inhibitor, as a drug candidate against BCR-ABL or T315I BCR-ABL positive cells and cancer (solid or leukemia), while it was less effective in other cell types tested." (PMID 27564101, 2016). "In particular, higher BCR/ABL-OOF expression levels were found in most undifferentiated hematopoietic CD34+ cells compared to CD34-cell population and indicate Rac as a new therapeutical target to block in order to inhibit leukemia stem cells." (PMID 26682280, 2015). "Together, our results suggest that the lack of IGF-IR on CML cells shifts BCR/ABL leukemia cell fate from CML to ALL." (PMID 25648584, 2015). "In contrast, expression of p210 from the endogenous BCR locus does not result in neoplastic transformation of hematopoietic cells to form leukemia." (PMID 24847444, 2014). "These cultures represent different genetically defined ALL subtypes, i.e. leukemias harboring the BCR-ABL, TEL-ABL or E2A-PBX1 translocation, or no recurring genetic abnormality." (PMID 24244612, 2013). "Overexpression of PECAM-1 in BCR/ABL-expressing cells, including K562 human leukemia cells, enhanced cell adhesion and partially inhibited imatinib-induced apoptosis involving mitochondria depolarization and caspase-3 cleavage, at least partly, in an ITIM-independent manner." (PMID 23233201, 2013). "However, the ability to signal downstream of the pre-BCR is selected against in Ph+ leukemias, and BCR-ABL1-mediated repression of pre-BCR-induced Ca2+ signaling has been described in Ph+ B-ALL patients, and in a mouse ALL model." (PMID 22693568, 2012). "Leukemias in these patients are clinically more similar to BCR-ABL1 induced CML, suggesting BCR may play a role in this particular pathogenesis." (PMID 22701616, 2012). "In accordance with data from extensive studies on the dose-dependent effects and time kinetics of IM we applied lower IM doses (range: 0.5 μM to 2.5 μM) for leukemia-derived BCR-ABL-positive cells (K562 and LAMA-84) than for BCR-ABL-negative cells (range: 2.5 μM to 10 μM)." (PMID 22870341, 2012). "Mice receiving donor cells transduced with BCR-ABL-iCre-GFP developed CML much faster that mice receiving donor cells transduced with BCR-ABL-GFP, with a higher percentage of myeloid leukemia cells and more severe infiltration of leukemia cells in the lungs." (PMID 21297225, 2010). "Because of limited availability of patient material, we did not study immunity to other known CML antigens such as WT1 or the BCR-ABL fusion region peptides, but we would expect that CTL immunity against these and perhaps other leukemia antigens should be similarly increased." (PMID 20668669, 2010). "SNIPER(ABL)-39 showed growth-inhibitory and protein knockdown effects in BCR-ABL-positive CML cell lines, such as KCL-22 (IC50 = 8.06 nM) and KU-812 (IC50 = 6.72 nM), but did not impact the growth of BCR-ABL-negative leukaemia lines like HL-60, MOLT-4, and Jurkat." (PMID 40793752, 2025). "Furthermore, we determined the percentage of Th17 cells in the leukemia niche in mice with secondary BCR-ABLtTA B-ALL cell transplantation treated with or without CXCL16." (PMID 38172124, 2024).
leukemia (continued). "One possible explanation for this discrepancy between transgenic models and knock-in models is that promoter activity of the bcr gene in the knock-in mice might not be sufficiently high for leukemia transformation by p210 BCR::ABL1." (PMID 35999358, 2023). "Notably, B-cell leukemia was developed in knock-in mice of p190 BCR::ABL1 cDNA, while leukemia progression was not confirmed in those of p210 BCR::ABL1." (PMID 35999358, 2023). "This table shows the BCR::ABL1-independent pathways and their inhibitors that could be used in combination with TKIs, and the stage of their current development for diseases listed that could be repurposed in the treatment of Ph+ leukaemias." (PMID 35884363, 2022). "Again, three recipients from each group were sacrificed on day 25, which revealed that the BCR/ABL1-Rora group recipients had a smaller gross splenic appearance with a significantly lower weight and significantly lower percentage and total number of leukemia cells." (PMID 35414788, 2022). "However, the mechanism of continuous TFR is still unclear, as there are “fluctuate” patients who have BCR–ABL-positive leukemia cells but do not observe obvious relapse." (PMID 34885012, 2021). "Finally, B lymphoblasts with BCR-ABL phenotype lacking BCL6 were not able to induce leukemia in immunodeficient mice." (PMID 32085659, 2020). "In another study using CRISPR/Cas9 genomic editing of the BCR-ABL fusion gene, García-Tuñón and his group were the first to report the use of CRISPR/Cas9 genome editing to abrogate the human BCR-ABL oncoprotein in leukemia cells as a therapeutic intervention." (PMID 32485885, 2020). "Our results reveal the role of oridonin as a small molecule proteostasis regulator that activates endogeneous HSF1 and support the potential clinical use of oridonin for BCR-ABL-expressing leukemia by inducing BCR-ABL degradation rather than inhibiting tyrosine kinase activity." (PMID 28128329, 2017). "This study supports previous work implicating NK cells as the major lymphoid population responsible for eradication of BCR/Abl-driven leukemias and suggests that STAT3-targeting strategies may severely impair NK-mediated antitumor immune responses in BCR/Abl leukemias." (PMID 27148255, 2016). "In order to further investigate the consequences of the co-expression of p96ABL/BCR and p185BCR/ABL for leukemogenesis, we addressed the question of whether the presence of p96ABL/BCR affects the phenotype or initiation of p185BCR/ABL-mediated leukemia." (PMID 25919613, 2015). "It is thought that leukemia stem cells (LSC) (primitive CML progenitor cells) may not be strictly addicted to BCR-ABL and to be able to bypass BCR-ABL signaling via other pathways when treated with TK inhibitors." (PMID 24913448, 2014). "Thus, BCR/ABL induces the MICA surface expression on CML leukemia cells, whereas it was absent on healthy hematopoietic cells." (PMID 24711808, 2014). "It is possible that these quiescent leukemia stem cells do not depend on BCR-ABL signaling." (PMID 24775308, 2014). "Despite activation of STAT5, the BCR-ABL triple mutant is not able to induce leukemia in vivo." (PMID 19823681, 2009). "Moreover, in the mice p210 BCR::ABL1‐transduced ALL model, in vivo conditional knockout of the integrin α6 gene sensitized the leukemia cells to nilotinib treatment, suggesting that the laminin/CD49f interaction might also be involved in the TKI‐resistance of Ph‐positive ALL." (PMID 38577721, 2024). "Accordingly, leukemic cells carrying the BCR–ABL, MLL–AF9 fusion proteins, and co-expressing HoxA9 and Meis1 were all affected by the inactivation of Pml in MSCs, thus suggesting the possibility that the same therapeutic intervention could be beneficial in multiple leukemia sub-types." (PMID 29302031, 2018).
leukemia (continued). "To test our RoCK and ROI targeted enrichment strategy, we used a mix of three patient-derived leukemia cell lines containing either a minor fusion (SUP-B15, e1a2), major fusion (K562, e14a2) or no BCR::ABL1 fusion (Loucy)." (PMID 41372142, 2025). "The NOPHO-ALL-92 and ALL-2000 trials found that compared with an initial diagnosis of leukemia with no CNS involvement, an initial diagnosis of CNS leukemia was more frequent in patients with T-ALL, hyperleukocytosis, and BCR/ABL fusion gene positivity." (PMID 36624786, 2022). "BCR/ABL1 (Philadelphia chromosome)-like ALL was initially identified as a subgroup of leukemias with a leukemic cell gene expression profile similar to that of BCR/ABL1-positive ALL and frequent IKZF1 alterations but without the BCR/ABL1 fusion." (PMID 33946897, 2021). "In order to verify the ability of HJB in human leukemia therapies, the effect of HJB on the HL60 cell line that represent a human promyelocytic leukemia cells BCR/ABL negative cells (acute myeloid leukemia) was investigated." (PMID 29950991, 2018). "The effect of serial passaging of Egr1-/-/BCR-ABL expressing cells, as done in colony assays, on their ability to promote leukemia compared to non-passaged cells would be informative." (PMID 29050203, 2017). "This approach is well represented by Ph-like leukemias, whose transcriptomes closely resemble those of conventional Ph-positive ALL, even in the absence of BCR-ABL translocations." (PMID 26943776, 2016). "Mice transplanted with BCR/ABL-transduced WT and IGF-IR cells had similar GFP+ cells at 3 months, suggesting IGF-IR is not essential for BCR/ABL leukemia propagation." (PMID 25648584, 2015). "Mice transplanted with BCR-ABL cells died around 12 days after the injection of 40,000 leukemia cells without treatment (Fig4C)." (PMID 25759362, 2015). "In primary leukemia samples obtained from BM of patients, we showed positive expressions of MKRN2 and RAF1 in B-ALL Philadelphia chromosome (BCR/ABL or Ph) positive and negative, T-ALL, AML and CML samples (n = 5–22)." (PMID 24675897, 2014). "Whereas the BCR-ABL fusion drives the initial chronic phase of the disease, the progression of CML involves additional genomic changes which make leukemia cells resistant to TKI therapy and independent of BCR-ABL." (PMID 23866735, 2013). "Similar findings were also observed in BCR/ABL-positive and -negative leukaemia cell lines and, interestingly, in solid tumour cell lines." (PMID 18728657, 2008). "Given the definitive relationship between oncogenic BCR-ABL and the occurrence of Ph+ leukemia, effective degradation of this fusion protein, rather than the inhibition of tyrosine kinase activity, would be a favorable choice to overcome a series of drawbacks of small molecule inhibitors." (PMID 38741123, 2024). "Leukemia was ruled out by FACS analysis and PCR for BCR-ABL." (PMID 35841421, 2023). "This unexpected result raises the possibility that DDR1 phosphorylates BCR also in CML and that BCR role in human cancer may not be restricted to leukaemia." (PMID 29438985, 2018). "While the mice with the null leukemia might show a delayed trend of death, the difference in types of leukemia did not significantly alter the survival of mice infected with WT and IGF-IR-null BCR/ABL cells." (PMID 25648584, 2015). "Tests for BCR/ABL and the leukemia-related fusion gene were negative." (PMID 23737874, 2013). "Since, as reported by these groups, mutation of these domains individually does not affect the interaction of BCR-ABL with its substrates, nor its ability to induce leukemia in mice, we focused our investigation on the triple mutant encompassing each of these component mutants in our studies." (PMID 19823681, 2009).
acute lymphoblastic leukemia (192 papers, 2002 to 2026). Leukemia with an acute onset, characterized by the presence of lymphoblasts in the bone marrow and the peripheral blood. "Philadelphia chromosome‐positive (Ph+) acute lymphoblastic leukemia (ALL) is a subtype of ALL that carries the BCR::ABL1 fusion gene, which encodes the constitutively active BCR::ABL oncoprotein." (PMID 40165400, 2025). "Some oncogenes influence the fate of stem cells: LMO2, BCR-ABLp190, and BCR-ABLp210 are specifically associated with and drive human T acute lymphoblastic, B acute lymphoblastic leukemia, and chronic myeloid leukemia (CML), respectively." (PMID 33807298, 2021). "Tyrosine kinase inhibitors that target the BCR/ABL mutation have been used as therapies of BCR/ABL positive acute lymphoblastic leukemia (ALL) with significant results." (PMID 33415044, 2020). "Resistance to tyrosine kinase inhibitors (TKIs) in patients with CML and Philadelphia chromosome-positive acute lymphoblastic leukemia (Ph-positive ALL) is frequently caused by mutations in the BCR-ABL kinase domain." (PMID 24481648, 2014). "Philadelphia chromosome-positive acute lymphoblastic leukemia (Ph+ ALL) is a distinct subtype of ALL characterized by the presence of the BCR::ABL1 fusion gene, which encodes a constitutively active BCR-ABL1 tyrosine kinase oncoprotein." (PMID 41170452, 2025). "Here, we report the case of a ponatinib-resistant Philadelphia chromosome-positive acute lymphoblastic leukemia (Ph + ALL) patient harboring a BCR::ABL1 p.I293_K294insSLLRD mutation." (PMID 39774950, 2025). "The multi-kinase inhibitor dasatinib has been implicated to be effective in pre-B-cell receptor (pre-BCR)-positive acute lymphoblastic leukemia (ALL) expressing the E2A-PBX1 fusion oncoprotein." (PMID 37686604, 2023). "Several studies have suggested that chemotherapy-free regimens consisting of blinatumomab and a BCR::ABL1 tyrosine kinase inhibitor are highly effective in Philadelphia chromosome-positive acute lymphoblastic leukemia (Ph + ALL)." (PMID 40369607, 2025). "An interesting study of deep molecular profiling revealed three transcriptomic subtypes of BCR::ABL1 lymphoblastic leukemia, each representing a maturation arrest at a stage of B-cell progenitor differentiation." (PMID 40076750, 2025). "Familial 46, XY Disorder of Sexual Development (DSD) was discovered in a Ph+, BCR::ABL1P210+ Acute Lymphoblastic Leukemia (ALL) female with RCBTB2::LPAR6 fusion gene." (PMID 39091920, 2024). "However, ABL1 KD mutations are relatively unstudied in BCR::ABL1‐positive acute lymphoblastic leukemia (ALL)." (PMID 39440695, 2024). "Studies in Philadelphia chromosome–positive acute lymphoblastic leukemia (ALL) showed that cells harboring the BCR-ABL fusion protein have elevated ROS levels that induced DSBs and genomic instability." (PMID 37301844, 2023). "The BCR::ABL1 gene most commonly leads to a blood cancer called chronic myeloid leukaemia (CML), but can also cause an acute leukaemia, more commonly acute lymphoblastic leukaemia and rarely, acute myeloid leukaemia." (PMID 38550948, 2023). "The child was diagnosed with acute lymphoblastic leukaemia (Pre-B-ALL, BCR/ABL p190 positive) 2 months ago and the risk stratification was set as high risk." (PMID 35820900, 2022). "For instance, the transcript e1a2 with the breakpoint in the minor breakpoint cluster region (m-BCR) producing a p190 protein was found initially in two-thirds of Ph+ acute lymphoblastic leukemia (ALL) patients." (PMID 33677711, 2021). "ROR1 has been shown to crosstalk with the B‐cell receptor (BCR) through the BCR complex and Bruton's tyrosine kinase (BTK) as well as with associated signaling molecules in acute lymphoblastic leukemia (ALL) B cells." (PMID 35844694, 2021). "Here the authors show distinct transcriptional profiles of B cell progenitors which are dependent upon pre-BCR and these profiles can be related to B cell transformation in lymphoblastic leukaemia." (PMID 34824268, 2021).